SST (somatostatin)
Diseases named in the same sentence as SST in open-access papers (continued):
Sharing a sentence is not in itself a finding about the gene and the disease.
colitis (5 papers, 2021 to 2024). Inflammation of the colon. "Direct evidence for the inhibitory role of SST in the inflammatory process in the large intestine was obtained in animal models of colitis." (PMID 38540191, 2024). "Differences in SST expression have been demonstrated depending on the colitis model, as well as between animal colitis and IBD in humans." (PMID 38540191, 2024). "In turn, in DSS-induced colitis in rats, a lower density of PP- and SST-positive cells was detected compared to control group, similarly to the results of IBD patients." (PMID 34829972, 2021). "In the colon, there was a lower number of epithelium SST-cells in colitis (Dextran-sulfate-sodium-induced) rat model and higher epithelium SST-cells in colitis (Trinitrobenzene sulfonic acid) rat model." (PMID 33796080, 2021). "However, due to divergent research results in IBD models, unclear mechanisms of action of SST, differences between colitis models and IBD in humans and different protein expression profiles in lamina propria in IBD and CRC, this study requires continuation." (PMID 38540191, 2024). "Moreover, studies in DSS-induced colitis and Citrobacter rodentium-infected colitis mouse models strongly suggest that upregulation of NHE8 by somatostatin ameliorates diarrheal symptoms in these colitis mouse models." (PMID 36142772, 2022). "Studies have also demonstrated that somatostatin, a neuroendocrine peptide, restored intestinal epithelial barrier function by upregulating claudin‐4 expression in mice with DSS‐induced colitis." (PMID 36799102, 2023). "There are differences regarding SST expression in IBD patients and animal models of colitis." (PMID 34829972, 2021).
Constipation (5 papers, 2014 to 2019). Infrequent or difficult evacuation of feces. "Effect of various samples on serum MTL (motilin), Gas (gastrin), ET (endothelin), SS (somatostatin), AchE (acetylcholine enzyme), SP (substance P) and VIP (vasoactive intestinal peptide) levels in activated carbon-induced constipation model mice." (PMID 25464378, 2014). "Regulation of gastrointestinal hormones, such as cholecystokinin (CCK), gastrin (GAS), somatostatin (SS) and motilin (MTL), may also be another important mechanism for improving the symptoms of LOP-induced constipation in animal models after ACCE administration." (PMID 35518898, 2019).
ischemia (5 papers, 2011 to 2021). A hypoperfusion of the BLOOD through an organ or tissue caused by a PATHOLOGIC CONSTRICTION or obstruction of its BLOOD VESSELS, or an absence of BLOOD CIRCULATION. "In particular, in recent years somatostatin and pituitary adenylate cyclase activating peptide have been reported to be highly protective against retinal cell death caused by ischemia, while data on opioid peptides, angiotensin II, and other peptides have also been published." (PMID 23814541, 2013). "In in vitro study, for example, SSTR2 agonist reduced the cell lost in rat retinal plant caused by chemical ischemia, and studies in knockout animals have shown that SST has neuroprotective effect in ischemia retinas." (PMID 26175842, 2015). "Activation of SST receptor-2 by SST or its analogues reportedly protects retinal neurons against ischemia-induced damage." (PMID 25268135, 2014). "Somatostatin (SST), an endogenous peptide, may exert anti-inflammatory and neuroprotective effects on retinal injury induced by ischemia." (PMID 26175842, 2015).
memory impairment (5 papers, 2015 to 2025). "The Cys-HCl-induced decrease in the somatostatin-positive cells in the cortical and hippocampal regions of the brains of Sprague–Dawley rats have been reported to be associated with considerable motor deficits and memory impairments." (PMID 39061373, 2024). "Together, these results suggest that SST-specific Arid1b haploinsufficiency leads to several learning and memory impairments." (PMID 32398858, 2020). "With aging, there is a decrease in somatostatin and GABAergic interneuron expression in the hippocampus; this results in increased excitatory activity at rest that is hypothesized to contribute to memory impairment in amnestic MCI." (PMID 26441635, 2015).
pancreatitis (5 papers, 2016 to 2026). Inflammation of the pancreas. "This is supported by the finding that the inhibitors of secretion, cholecystokinin antagonist and somatostatin, ameliorate pancreatitis when introduced early in experimental settings." (PMID 40254129, 2026). "Since there were no worsening clinical symptoms, such as a fever or increased abdominal pain, protease inhibitors, somatostatin analog, and antibiotics were started for pancreatitis, resulting in a prompt reduction of the drain amylase level to 1,973 U/ml." (PMID 38654373, 2024). "One case of mild pancreatitis (clinical manifestations of abdominal pain, combined with CT and blood amylase examination to confirm the diagnosis, fasting, somatostatin inhibition of pancreatic juice secretion, application of antibiotics, and nutritional support treatment improved after treatment)." (PMID 35294916, 2022).
somatotropinomas (5 papers, 2013 to 2023). "Wildemberg showed that low SSTR2 expression can predict the failure of somatotropinomas to respond biochemically to SST analog treatment." (PMID 37900156, 2023). "However, the role of AIP overexpression under certain stimuli, for instance, in somatotropinomas treated with somatostatin analogues, might have a role on the posttranscriptional regulation of other proteins." (PMID 29507682, 2018). "SSTR5 is also expressed in abundance on somatotropinomas, providing rationale for the use of pasireotide in patients uncontrolled on SSTR2-preferential first-generation somatostatin analogues." (PMID 32217809, 2020).
acute pancreatitis (4 papers, 2006 to 2025). An acute inflammatory process that leads to necrosis of the pancreatic parenchyma. "According to the pathophysiology of acute pancreatitis, the efficacy of the drugs already available, such as gabexate mesilate, lexipafant and somatostatin should be re-evaluated and should be probably administered in a different manner." (PMID 16759369, 2006). "Furthermore, the results suggest that cannabinoid HU210, the CB1/2 receptor agonist, has the therapeutic potential for AGML in acute pancreatitis by attenuating inflammation and restoring gastrin/somatostatin equilibrium, and then decreasing the secretion of gastric acid and pepsin." (PMID 23285225, 2012). "When gastrin or somatostatin secretion fails to maintain a basic equilibrium, the surplus pepsin and acid release disproportionally, resulting in damages and dysfunctions of the stomach during acute pancreatitis." (PMID 23285225, 2012).
amyloid (4 papers, 2017 to 2025). "While the review focuses on Aβ and SST, it is to be anticipated that crosstalk amongst functional and disease-associated amyloids will emerge as a general theme with much broader significance in the etiology of dementias and other amyloidosis." (PMID 32309597, 2017). "It indicates that both amyloidosis and aging affect the distribution of SST interneurons in the mouse brain." (PMID 40012738, 2025). "In this study, we seek to compare the effects of aging and amyloidosis in adult 5xFAD mice in terms of alterations in the density of inhibitory and excitatory synapses, and densities of PV and SST interneurons in various brain regions." (PMID 40012738, 2025). "In the TgCRND8 amyloid model, there is a subregion- and lamina-specific decrease of SST-expressing interneurons primarily in stratum oriens of CA1, CA2 and stratum radiatum of CA3." (PMID 37841892, 2023). "In summary, SST INs present an intriguing target for modulating AD pathophysiology due to their targeting of pyramidal neuron dendrites, partial resilience to neurodegeneration, and potential influence over amyloidosis and tauopathy." (PMID 37841892, 2023). "Indeed, hippocampal amyloid injection causes loss of subset of SST INs in CA1 stratum oriens that do no co-express NPY or PV." (PMID 37841892, 2023).
bladder cancer (4 papers, 2020 to 2022). "The application of somatostatin showed a dramatic decrease of the incidence of bladder cancer due to the carcinogenic effect of nitrosamine in rats, suggesting a protective effect possibly by supporting apoptosis of dysplastic cells at risk malignification." (PMID 34601710, 2022). "All nine urinary methylation markers (FAM19A4, GHSR, MAL, miR-129, miR-935, PHACTR3, PRDM14, SST and ZIC1) showed significantly higher methylation levels in bladder cancer patients than in controls (p < 0.001)." (PMID 35123558, 2022). "The urinary methylation levels of FAM19A4, GHSR, MAL, miR-129, miR-935, PHACTR3, PRDM14, SST and ZIC1 were significantly higher in patients with bladder cancer than in controls (all, p < 0.001)." (PMID 35123558, 2022). "We found that the methylation levels of markers GHSR, SST, and ZIC1 were higher in natural voided urine (all, Mann–Whitney U test: p < 0.001) of bladder cancer patients than in the natural voided urine of benign hematuria controls." (PMID 33572525, 2021). "These encompass seven protein-coding genes (FAM19A4, GHSR, MAL, PHACTR3, PRDM14, SST and ZIC1)—of which, the CpG islands are methylated in bladder cancer—as well as two miRNAs (miR-129 and miR-935) with promoter regions that are also known to be methylated in bladder cancer." (PMID 32252299, 2020).
cholelithiasis (4 papers, 2018 to 2025). The presence of crystallized deposits forming in the gallbladder or biliary tree, primarily composed of cholesterol, bilirubin, and bile. "However, SST analog therapy is generally associated with multiple adverse effects, such as cholelithiasis, enterocolitis, and growth retardation, due to the wide distribution of SST receptors in numerous tissues." (PMID 29880854, 2018).
chronic pancreatitis (4 papers, 2020 to 2025). A chronic inflammatory process causing damage and fibrosis of the pancreatic parenchyma. "The use of somatostatin (SST) peptide in the treatment of chronic pancreatitis is limited by its short half-life and potential side effects." (PMID 41050416, 2025). "The recovery of SST by MP-SST downregulated the expressions of chronic pancreatitis-related factors and alleviated the histologic severity of the pancreas to the greatest extent compared to other treatment groups." (PMID 36365160, 2022). "In summary, a polymer-supported and biomimetic membrane surface-coated nanoparticulate platform was developed for therapeutic delivery of SST peptide to alleviate the severity of chronic pancreatitis." (PMID 36365160, 2022). "In this study, a macrophage membrane-coated poly(lactic-co-glycolic acid) (PLGA) nanodelivery system was developed to enhance the bioavailability of the somatostatin (SST) peptide, which faces the hurdles of short half-life and potential side effects in the treatment of chronic pancreatitis." (PMID 36365160, 2022). "Hypermethylation of the SST gene (encoding somatostatin) and concomitant downregulation of its expression were discovered in PDAC and endocrine tumor tissues while not being present in chronic pancreatitis (inflamed) tissues and normal pancreas." (PMID 32243066, 2020).
Cirrhosis (4 papers, 2014 to 2023). A chronic disorder of the liver in which liver tissue becomes scarred and is partially replaced by regenerative nodules and fibrotic tissue resulting in loss of liver function. "Finally, other pathways have been involved in hepatocyte cell proliferation and cirrhosis, including growth hormone (GH), insulin-like growth factors (IGF1 and IGF2), the PI3K/AKT pathway, somatostatin (SST), and MAPK signaling." (PMID 38067261, 2023). "Currently, non-selective β blockers, vasopressin analogues, and somatostatin analogues are commonly used to prevent portal hypertensive bleeding in cirrhosis." (PMID 35370660, 2022).
corticotroph adenoma (4 papers, 2015 to 2024). "However, BIM-23A760 elicited stimulatory effects in a subset of GHomas, ACTHomas and NFPAs in terms of Ca2+ signaling and/or hormone secretion, which was associated with the relative somatostatin/dopamine-receptors levels, especially sst5 and sst5TMD4." (PMID 28181484, 2017). "It needs to be clarified how the SSTR expression in corticotroph adenomas is influenced by somatostatin analogs and changes of cortisol levels, especially since an effective medical treatment would be applied for a longer period or even permanently." (PMID 30627156, 2018).
COVID-19 (4 papers, 2022 to 2024). A disease caused by infection with severe acute respiratory syndrome coronavirus 2. "Quantitative analysis demonstrated that, compared with the control pancreatic tissues, somatostatin+ δ cells (reduced by 72.47%) were significantly decreased in COVID-19 patients’ samples." (PMID 38609366, 2024). "Five hub genes, including GAD2, SST, TAGLN3, SYP, and KCNJ4, were further verified using the test_datasets of COVID-19, AD, and PD." (PMID 36902271, 2023). "Of note, transcripts of the somatostatin precursor gene (SST) were downregulated only in virus-negative COVID-19 cases (FC = −1.6, FDR = 0.17) but did not changed in virus-positive specimens." (PMID 37246981, 2023).
cyst (4 papers, 2008 to 2025). A sac-like closed membranous structure that may be empty or contain fluid or amorphous material. "Additionally, somatostatin decreases cAMP production and somatostatin agonists have also been tested clinically, although with less success than tolvaptan, potentially because of the downregulation of receptors associated with cyst growth." (PMID 31336917, 2019). "The cyst mucosa showed numerous endocrine cells located in the gastric glands (gastrin, somatostatin and serotonin), the duodenal glands (serotonin, somatostatin, secretin, gastrin and bombesin) and the small-intestinal glands (serotonin, somatostatin, secretin and bombesin)." (PMID 18498655, 2008).
dementia (4 papers, 2012 to 2024). Loss of intellectual abilities interfering with an individual's social and occupational functions. "However, as we show that SST-14 levels are maintained despite Aβ burden in the AD-resilient vs AD-dementia brain, SST likely has roles in cognition beyond these putative interactions with Aβ." (PMID 38531951, 2024). "Clinical studies have demonstrated a link between AD-related dementia and alterations in GABA or somatostatin levels in the brain and CSF that are exacerbated by apoE4." (PMID 23300939, 2012).
diabetic retinopathy (4 papers, 2017 to 2023). "In diabetic retinopathy (DR), there is a downregulation of retinal expression of SST, which is associated with a dramatic decrease in intravitreal SST levels in both Proliferative Diabetic Retinopathy (PDR) and Diabetic Macular Edema (DME)." (PMID 32784955, 2020). "A somatostatin deficit has been proven to trigger apoptosis and glial activation during diabetic retinopathy." (PMID 33466261, 2021). "Topical brimonidine and somatostatin had been shown to act as neuroprotectants and seem to attenuate morbidity due to background diabetic retinopathy (BDR) as well as any deterioration of BDR into PDR." (PMID 28709426, 2017). "However, only somatostatin has so far been tested in a randomised clinical trial (the European Consortium for the Early Treatment of Diabetic Retinopathy [EUROCONDOR] study)." (PMID 37277664, 2023). "The underlying molecular processes of SST- and PACAP-receptor signaling include the inhibition of proapoptotic molecules (e.g., caspase-3, caspase-8, FasL and calpain-2), meaning that they could be very well suited for reducing the harmful effects of diabetic retinopathy." (PMID 33466261, 2021).
gallstones (4 papers, 2019 to 2025). Solid crystalline precipitates in the biliary tract, usually formed in the gallbladder, resulting in the condition of cholelithiasis. "Lastly, per current consensus guidelines, prophylactic cholecystectomy should be performed at the time of debulking surgery as the patient is likely to require long-term somatostatin analogs and is at higher risk for gallstone formation." (PMID 37048539, 2023). "Treatment with somatostatin analogs is commonly associated with gallstone formation, although this rarely is symptomatic or requires surgery." (PMID 31379734, 2019). "The effect of somatostatin analogs on gallbladder and secondary development of gallstones is well known." (PMID 31352317, 2019).
gastric atrophy (4 papers, 2009 to 2025). "In contrast, the anti-inflammatory Th2 cytokine IL-4 stimulates the secretion of somatostatin, thereby decreasing the development of gastric atrophy." (PMID 19270747, 2009).
lung carcinoma (4 papers, 2017 to 2023). "Active targeting was achieved by surface modification or functionalization of the nanoparticle using a substrate of receptors that are overexpressed in lung cancer cells (e.g., folic acid, somatostatin)." (PMID 33499040, 2021). "In this review, we suggest the use of a panel consisting of eight tumor-associated biomarkers—CEA, CYFRA21-1, ProGRP, CEA, PSF3, MUC, SCCA, and SST—allow us to differentiate between each histological type of lung cancer and to define the metastasis rate." (PMID 29137182, 2017).
metastatic disease (4 papers, 2013 to 2022). "The first step in the management of patients with metastatic well-differentiated ANENs is to determine factors that may impact therapeutic strategies such as tumor grade, site of metastatic disease (hepatic vs. extra-hepatic), tumor burden, and the status of somatostatin expression." (PMID 36612291, 2022). "In addition, the primary and metastatic tumors of this individual also shared high expression of the RNA encoding ghrelin; however, neither metastatic tumor carried over the expression pattern of GCG and SST RNAs seen in the primary." (PMID 30062048, 2018). "No cells in the metastatic tumors stained positive for insulin, somatostatin, or pancreatic polypeptide Y." (PMID 26192435, 2015).
mood disorder (4 papers, 2013 to 2022). A cognitive disorder a disturbance in which the person's mood is hypothesized to be the main underlying feature. "Research advances over the past three decades suggest a critical role for somatostatin in the pathophysiology of mood disorders, and potential new therapeutic strategies." (PMID 24058344, 2013). "Hence, despite these early findings, interest in somatostatin in mood disorders has declined over time." (PMID 24058344, 2013). "Combined validation of independent datasets has shown that dysregulated mRNA expression of SST and CRHBP is shared in MDD-BP, and this plays a critical role in the etiology of mood disorders." (PMID 36081461, 2022).
Peptic ulcer (4 papers, 2015 to 2025). The term peptic ulcer refers to acid peptic injury of the digestive tract, resulting in mucosal break reaching the submucosa. "Gingerol treatment significantly enhances the secretion of gastrin and somatostatin, reducing the risk of peptic ulcer." (PMID 39234535, 2024). "We speculate that TLR4–ligand interaction in G and D cells could have a direct effect in the gastrin and somatostatin secretion, respectively, and potentially explain the associations between the TLR4 polymorphisms and increased serum gastrin and the peptic ulcer risk." (PMID 26161647, 2015).